MSANTD2-AS1 (MSANTD2 antisense RNA 1)
Synonyms: BCLET
Gene: Long non-coding RNA gene on chromosome 11 (124,800,424 to 124,834,487, forward strand). Ensembl gene ENSG00000245498.
Diseases named in the same sentence as MSANTD2-AS1 in open-access papers:
MSANTD2-AS1 is named in the same sentence as 3 diseases in open-access papers, as found by Europe PMC text mining. Sharing a sentence is not in itself a finding about the gene and the disease.
MSANTD2-AS1 shares sentences with these, for which no sentence is quoted: bladder (1 paper); bladder cancer (1); tumor (1).